CRP (C-reactive protein)
Diseases named in the same sentence as CRP in open-access papers (continued):
Sharing a sentence is not in itself a finding about the gene and the disease.
metabolic syndrome (continued). "The concentration of 5-HIAA was reported to be associated with highly sensitive C-reactive protein, which was a marker of chronic low-grade inflammation in metabolic syndrome." (PMID 31919742, 2020). "This process is also associated with the discharge of proinflammatory markers as well as fibrinogen and C-reactive protein that altogether act in concert with dyslipidemia to increase the whole cardiovascular risk of a person." (PMID 32952834, 2020). "Linear and group trends were determined using regression analyses for liver enzymes, cardiovascular risk factors, weight parameters, glucose, metabolic syndrome, and C-reactive protein." (PMID 32968670, 2020). "Univariable and multivariable linear regression analysis of high sensitivity C-reactive protein, android fat mass, gynoid fat mass, and android to gynoid ratio against the metabolic syndrome risk components." (PMID 32226033, 2020). "The degree of cardiorespiratory fitness in metabolic syndrome subjects has been shown to have inverse associations with CRP, IL-6, and IL-18, partially explained by the degree of abdominal obesity." (PMID 31331009, 2019). "The odds ratios for the components of metabolic syndrome and CRP also explained a U-shaped association with sleep duration in volunteers with or without insomnia symptoms." (PMID 31404954, 2019). "So far, we have widely recognized that the top risk factors related to CAD include aging, dyslipidemia, hypertension, smoking, diabetes, metabolic syndrome, hyperhomocysteinemia, and C-reactive protein." (PMID 31781165, 2019). "This study indicated that insomnia symptoms were significantly associated with the components of metabolic syndrome and CRP." (PMID 31404954, 2019). "Though we did not directly measure hepatic enzyme activities as markers of liver function, elevated CRP levels have been associated with higher alkaline phosphatase and alanine aminotransferase activities in metabolic syndrome subjects." (PMID 31209255, 2019). "A number of studies have reported positive associations between circulating concentrations of CRP and IL-6, and the risk of cardiovascular disease, cancer, metabolic syndrome, and type 2 diabetes mellitus." (PMID 31546602, 2019). "Medium to high tertiles of CRP were associated with metabolic syndrome and its components (waist circumference, triglyceride, and high-density lipoprotein (HDL) cholesterol), body mass index, and uric acid." (PMID 30999680, 2019). "There are also studies suggesting that elevated serum CRP levels are associated with metabolic syndrome." (PMID 31372137, 2019). "A cross-sectional study (486 Tehrani female teachers) observed that women in the highest quintile of fruit intake had a 34% lower risk of metabolic syndrome and 25% reduction in CRP levels compared to women eating the lowest fruit intake." (PMID 30487459, 2018). "Body fat and BMI were also significantly associated with CRP in obese males and females with metabolic syndrome and heart failure." (PMID 30454030, 2018). "Total fiber intake was inversely associated with obesity, metabolic syndrome and elevated CRP risk among US adults in the NHANES 1999–2010 analysis." (PMID 30487459, 2018). "The measurement of CRP is useful in the diagnosis and monitoring of many acute and chronic inflammatory conditions, including obesity and the metabolic syndrome, which can cause elevations of hs-CRP in the range of 3–10 mg/L." (PMID 30190688, 2018). "This is the first study to manifest sex-related differences in the association among EAT thickness, hs-CRP level, and myocardial function in middle-aged subjects with suspected metabolic syndrome." (PMID 29960588, 2018). "Currently in clinical settings, biomarkers of CVD risk, including elevated CRP, and dyslipidemia determine intermediate phenotypic presentation of CVD and predict 10-year risk of CVD events." (PMID 30138332, 2018).
metabolic syndrome (continued). "Increased CRP levels have been extensively associated with increased BMI and therefore metabolic syndrome and cardiovascular risk." (PMID 30190688, 2018). "Body Mass index has been extensively associated with increased CRP in SZ subjects; and increased CRP has been identified as a risk factor for metabolic syndrome and cardiovascular risk in SZ subjects." (PMID 30190688, 2018). "The physical health studies have confirmed that increased CRP levels was a predictor of metabolic syndrome and cardiovascular risk in SZ subjects." (PMID 30190688, 2018). "High TG, body fat, and CRP are factors linked to the metabolic syndrome which increases the overall cardiovascular risk." (PMID 30729041, 2018). "It is reported that ABCA1 gene polymorphisms are associated with dyslipidemia and the production of some inflammatory cytokines including IL-6 and C-reactive protein (CRP)." (PMID 29724005, 2018). "The primary cardiovascular disease risk markers that are routinely investigated in schizophrenia include metabolic syndrome, Framingham 10-year Relative Risk score, C-reactive protein, and dyslipidemia." (PMID 28396623, 2017). "The impact of CRP and markers of atherogenic dyslipidemia on CVD risk is often underestimated in clinical practice, with a lack of evidence for the prevalence and treatment of the latter." (PMID 28623902, 2017). "The association of markers of atherogenic dyslipidemia with CRP levels was found to be significant only after adjusting for confounding factors among patients with low HDL-C levels." (PMID 28623902, 2017). "CRP is a sensitive marker of inflammation, and elevated levels have been associated with the risk of coronary artery disease and metabolic syndrome." (PMID 29056890, 2017). "These patients are likely to be at an even higher risk of CVD than those with either atherogenic dyslipidemia or elevated CRP levels alone." (PMID 28623902, 2017). "With respect to this point, we found a significant association between OPG and CRP, not only in the hypertensive patients selected for this study, but also in patients with metabolic syndrome that we selected for a previous study." (PMID 28683789, 2017). "In a clinical study, the plasma resistin level was associated with coronary atherosclerosis independently of metabolic syndrome and CRP." (PMID 27649254, 2016). "LPS levels correlated with body fat percentage (r = 0.209, p = 0.04) and C-reactive protein (r = 0.513, p<0.001) confirming its association with markers of the metabolic syndrome and inflammation." (PMID 27992443, 2016). "The role of the decreased IgG antibody response to A. actinomycetemcomitans, increased C-reactive protein levels on the association between periodontal disease and metabolic syndrome in a group of Thai patients is suggested." (PMID 26871443, 2016). "Vuksan-Cusa also reported elevated CRP levels associated with the risk of new onset metabolic syndrome." (PMID 27547191, 2016). "Plasma C‐reactive protein (CRP) concentration is associated positively with cardiovascular risk, including dyslipidemia." (PMID 27633999, 2016). "There is a strong correlation between circulating CRP levels and anthropometric markers and body composition, and CRP has been proposed as a screening tool to assess the risk of the metabolic syndrome in youth." (PMID 27258304, 2016). "Subclinical inflammation is associated with insulin resistance, and CRP has emerged as one of the best predictors of vascular inflammation, metabolic syndrome and cardiovascular disease." (PMID 27258304, 2016). "In one study of women with metabolic syndrome, those with hs-CRP >3.0 mg/l had twice the risk of future cardiovascular events compared to those with hs-CRP <3.0 mg/l." (PMID 25933642, 2015). "Higher levels of CRP and leptin were shown to be associated with increased metabolic syndrome components." (PMID 25994228, 2015).
metabolic syndrome (continued). "The risk of adult obesity, metabolic syndrome, hyperglycaemia or type 2 diabetes, and elevated level of high-sensitivity CRP increased with a rise in childhood BMI and skinfold thicknesses, irrespectively of BMI gain from childhood to adulthood." (PMID 25880559, 2015). "An stronger association between ferritin levels and metabolic syndrome was detected in studies adjusted by CRP [OR = 1.92 (95% CI: 1.61, 2.30; I2 = 78%)] compared to studies that did not adjust by CRP [OR = 1.52 (95% CI: 1.36, 1.69; I2 = 41%)]." (PMID 24884526, 2014). "Various features associated with metabolic syndrome correlate negatively with PTX3 levels but positively with CRP." (PMID 24705587, 2014). "We have also shown that, in the overall population, CRP levels are positively associated with BMI, HbA1c levels and the number of components of the metabolic syndrome present, and are negatively associated with HDL-C levels." (PMID 24564178, 2014). "CRP levels were also higher in women, those at higher traditionally estimated cardiovascular risk and those with greater numbers of metabolic syndrome markers." (PMID 24564178, 2014). "Elevated CRP levels were noted when patients experienced chronic inflammation caused by conditions such as cardiovascular disease, metabolic syndrome, and colorectal cancer." (PMID 25371597, 2014). "Our study confirms findings from several previous investigations that have reported a significant association between elevated CRP and dyslipidemia." (PMID 24558466, 2014). "Leptin remained independently associated with metabolic syndrome risk after additional adjustment for adiposity, cytokines, and CRP." (PMID 24455217, 2013). "We found the combination of positive CRP with dyslipidemia to be significantly associated with a deficiency of 25-hydroxyvitamin D. One of the recent study advocated the association of positive CRP with 25-hydroxyvitamin D." (PMID 24455278, 2013). "The combination of the associated markers that is, elevated CRP with dyslipidemia, had a more robust association with 25-hydroxyvitamin D deficiency compared to normal 25-hydroxyvitamin D groups (P = 0.002)." (PMID 24455278, 2013). "Deficiency of 25-hydroxyvitamin D was significantly associated with dyslipidemia (P = 0.0001), mean serum glucose (P = 0.0002) mean CRP (P = 0.04), and mean alkaline phosphatase (P = 0.01)." (PMID 24455278, 2013). "On comparison between subjects with normal versus deficiency 25-hydroxyvitamin D levels, significant association was seen with dyslipidemia (P = 0.02) and elevated CRP (P = 0.004) in 25-hydroxyvitamin D deficiency group." (PMID 24455278, 2013). "When the analysis was further adjusted for adiposity measures in model 2 and cytokines and CRP in model 3 there was some attenuation in the association between leptin and the risk of metabolic syndrome, but the results remained significant." (PMID 24455217, 2013). "In month 3, the average CRP levels decreased only slightly, possibly due to the fact that most subjects had mild dyslipidemia with low risk of coronary heart disease and their initial CRP levels were rather low." (PMID 23484158, 2013). "Upon additional adjustment for BMI, the association of CRP with metabolic syndrome score remained significant in both male and female subjects (P < 0.001)." (PMID 22533665, 2012). "The objective of the present study was to determine if CRP and leptin levels are associated with cardiovascular disease risk factors as well as metabolic syndrome score in healthy Taiwanese adults." (PMID 22533665, 2012). "Both leptin and CRP levels were associated with cardiovascular risk factors as well as metabolic syndrome score in both men and women although gender-specific differences were observed." (PMID 22533665, 2012).
metabolic syndrome (continued). "The associations between CRP and/or leptin levels and cardiovascular risk factors and metabolic syndrome were determined using independent two sample t-tests to detect gender differences and chi-square tests to evaluate differences in frequencies." (PMID 22533665, 2012). "The associations between leptin and CRP levels with metabolic syndrome score, which is determined as the number of metabolic syndrome components described by the ATP III criteria, was next determined." (PMID 22533665, 2012). "Further studies are necessary to determine if adipose inflammation alters the association of CRP and leptin with metabolic syndrome in obese individuals." (PMID 22533665, 2012). "This is the first study to explore the possible association and interaction between leptin and CRP levels with risk factors for cardiovascular disease and metabolic syndrome in a Taiwanese population." (PMID 22533665, 2012). "In this study, further associations between leptin and CRP levels and metabolic syndrome score were detected in both male and female participants." (PMID 22533665, 2012). "Increased PAI-1act, BMI, HbA1c, triglycerides, the metabolic syndrome, fibrinogen concentration, CRP, female sex and positive HIV status were associated with increased CLTs, while habitual alcohol consumption associated with decreased CLT." (PMID 23145007, 2012). "In middle-aged subjects, high leptin in men and high CRP in women were significant predictors of metabolic syndrome; those with elevations in both markers had the highest risk of developing metabolic syndrome." (PMID 22533665, 2012). "High sensitivity C-reactive protein (hs-CRP), a marker of systemic inflammation and a predictor of type 2 diabetes and cardiovascular disease, is associated with the metabolic syndrome and its separate components." (PMID 22417460, 2012). "In the Cardiovascular Risk in Young Finns Study, high CRP levels were one of the determinants in youth for the incidence of adult metabolic syndrome." (PMID 21513530, 2011). "To test the interaction between the CRP polymorphisms and affective status on risk of the metabolic syndrome, we grouped the genotypes into binary variables according to the existing literature on the effect of these polymorphisms on plasma CRP concentration." (PMID 21296145, 2011). "Adolescent emotional problems play an important role in the development of the metabolic syndrome later in life, particularly in those homozygous for the major allele of CRP rs1205." (PMID 21296145, 2011). "We also show that a CRP polymorphism modifies the association between adolescent affective status and the metabolic syndrome." (PMID 21296145, 2011). "In healthy prepubertal children an association between CRP, fasting insulin, dyslipidemia, blood pressure and adiposity has been found." (PMID 21513530, 2011). "Genetic loci associated with serum levels of biomarkers related to the metabolic syndrome such as C-reactive protein (CRP) have also been identified." (PMID 20661421, 2010). "Ultrasensitive C-reactive protein (CRP) is a systemic inflammatory and cardiovascular biomarker that is associated with endothelial dysfunction and metabolic syndrome." (PMID 20963365, 2010). "Multiple linear regression analysis adjusting for age, gender and components of metabolic syndrome, log CRP was also independently associated with log HOMA-IR (β coefficient, 0.168; P < 0.001) and WC (β coefficient, 0.131; P = 0.006)." (PMID 21167068, 2010). "In a recent study on the MDCS cohort, we found that low SEP was strongly associated with CRP levels, independently of potential mediating factors e.g., smoking and factors involved in the metabolic syndrome." (PMID 18518944, 2008). "In combination, these and other genetic studies related to less direct correlates of atherosclerosis, such as blood pressure and metabolic syndrome provide evidence against the status of CRP as a causal factor for atherosclerosis." (PMID 18714381, 2008).
metabolic syndrome (continued). "Patients with NAFLD are well known to have metabolic syndrome, and increasing number of metabolic syndrome risk factors is associated with increasing CRP." (PMID 19014569, 2008). "Elevated levels of serum CRP are associated with the metabolic syndrome and cardiovascular disease, and is therefore a relevant risk factor to identify by non-invasive markers such as SAD." (PMID 17391519, 2007). "All of the characteristics of metabolic syndrome are also modestly associated with elevated levels of CRP." (PMID 17140429, 2006). "However, this study did not analyze the gender-specific associations between specific blood lipid indicators and CRP or reveal a complex interaction effect among BMI, CRP, and dyslipidemia." (PMID 40864980, 2025). "However, we observed significant differences in parameters related to carbohydrate and lipid metabolism—key components associated with the risk of metabolic syndrome—as well as in the concentrations of proinflammatory markers, including IL-1β, IL-6, and CRP." (PMID 40944273, 2025). "Also, one previous study found that a low-fat diet combined with physical activity including brisk walking, jogging, or running was associated with lower CRP levels in women with metabolic syndrome." (PMID 38542799, 2024). "The joint association of elevated CRP levels and dyslipidemia with stroke." (PMID 39247228, 2024). "The association between serum ferritin and metabolic syndrome may be confounded by body mass index and C-reactive protein levels." (PMID 39410926, 2024). "Consequently, further research is warranted to assess the predictive capacity of elevated CRP levels and dyslipidemia for stroke risk over an extended period of observation." (PMID 39247228, 2024). "The objective was to enroll participants with metabolic syndrome plus elevated CRP concentrations of ≥3 mg/L, indicative of a high risk for CVD, into a double-blind randomized placebo-controlled trial of a high vitamin C micronutrient supplement versus placebo control for 12 weeks duration." (PMID 38671852, 2024). "Associations between circulating OC and different parameters of metabolic syndrome were tested also by others: increased serum OC correlates inversely with BMI, C-reactive protein (CRP), insulin, and TG and is independently associated with changes in CRP." (PMID 38542487, 2024). "Other data suggested that inflammation might partially mediate the association between dyslipidemia and cardiovascular diseases, showing a strong correlation between dyslipidemia and hs-CRP levels." (PMID 39200151, 2024). "The inclusion of one or more pro-inflammatory cytokines that are associated with the metabolic syndrome, e.g., CRP, and/or likely to increase IGFBP-1 production, e.g., IL-6, could help in assessment at the individual level." (PMID 39595651, 2024). "In conclusion, the findings of our study demonstrate that the co-occurrence of elevated CRP levels and dyslipidemia may heighten the susceptibility to stroke in middle-aged and older adult individuals in China." (PMID 39247228, 2024). "CRP is positively associated with the metabolic syndrome and may be an independent risk factor in patients with CAD." (PMID 37081535, 2023). "The International Diabetes Federation (IDF) issued in 2007 a guideline on pediatric metabolic syndrome and among other directions in need of research, a call for more investigations regarding the association between high-sensitivity C-reactive protein (hsCRP) and MetS in children was made." (PMID 38001962, 2023). "Lactic acid bacteria (i.e., Lactobacillus coryniformis, Lactobacillus ruminis, Weissella confusa, and Weissella cibaria) were positively correlated with metadata associated with IR, increased abdominal circumference, dyslipidemia, and inflammation (CRP levels)." (PMID 37342535, 2023).